TIMP1 (TIMP metallopeptidase inhibitor 1)
Diseases named in the same sentence as TIMP1 in open-access papers (continued):
Sharing a sentence is not in itself a finding about the gene and the disease.
Cachexia (5 papers, 2018 to 2025). Severe weight loss, wasting of muscle, loss of appetite, and general debility related to a chronic disease. "We then separated the effects of jaundice and cachexia within our cohort to test their individual associations with TIMP-1 levels." (PMID 29394913, 2018). "We report for the first time that TIMP-1 was associated with presence of cachexia and cachexia-associated clinical markers, and conclude that TIMP-1 should be further evaluated as a cachexia biomarker." (PMID 29394913, 2018). "We report that TIMP-1 was associated with clinical markers of cachexia and with presence of cachexia in our cohort." (PMID 29394913, 2018). "Elevated plasma TIMP-1 levels were also associated with clinical cachexia markers, including absolute and relative values of weight loss and lung function, as well as ferritin, hemoglobin, and cholinesterase levels." (PMID 29394913, 2018). "We report that TIMP-1 was associated with clinical markers of cachexia and also with the presence of cachexia but only in patients without jaundice." (PMID 29394913, 2018). "TIMP-1 levels in these patients were tested for asscociation with jaundice and chachexia, and furthermore correlated with cachexia-related clinical parameters such as weight loss and ferritin, parameters of lung function, hemoglobin and liver synthesis parameters." (PMID 29394913, 2018). "Several laboratory (hemoglobin, ferritin, serum cholinesterase) and clinical parameters (relative and absolute weight loss, spirometry tests FEV1 and FVC) known to be associated with cachexia exhibited a significant correlation with plasma TIMP-1 levels in our study." (PMID 29394913, 2018). "This shows a clear association of TIMP-1 plasma levels with clinical markers of cachexia." (PMID 29394913, 2018). "Furthermore, exclusion of jaundice patients revealed a clear association of TIMP-1 plasma levels with cachexia in CP and PDAC patients." (PMID 29394913, 2018). "When ordinal regression was performed using cachexia status as the response variable and TIMP-1 and GDF-15 as predictor variables (dichotomized), GDF-15 remains significant as a predictor (P=0.021)." (PMID 39989973, 2025). "We show that TIMP-1 was counterindicated as a marker in patients with jaundice, while TIMP-1 together with cachexia appeared as a promising combination of prognostic parameters." (PMID 29394913, 2018). "As plasma TIMP-1 levels were elevated in both, cachexia and jaundice patients due to the individual conditions, it is likely that the effects of concomitant jaundice weaken the association between TIMP-1 and cachexia." (PMID 29394913, 2018). "We also found significantly higher TIMP-1 levels in patients with cachexia in the jaundice-free subgroup of our cohort." (PMID 29394913, 2018). "Thus, plasma TIMP-1 levels are elevated in both, cachexia and jaundice patients due to the individual condition." (PMID 29394913, 2018). "This retrospective study reports for the first time that plasma levels of TIMP-1 are associated with pancreatic lesion-induced cachexia in patients without jaundice." (PMID 29394913, 2018). "We further determine the usefulness of plasma TIMP-1 levels as a cachexia biomarker." (PMID 29394913, 2018). "Next, we tested whether elevated TIMP-1 levels in cachexia may suggest a potential use as cachexia biomarker." (PMID 29394913, 2018). "This is by the observation that jaundice and cachexia patients had higher plasma TIMP-1 level." (PMID 29394913, 2018). "It is tempting to propose the use of TIMP-1 as cachexia marker, i.e. due to its involvement in muscle remodeling in cancer cachexia, which may allow for detection of early muscle wasting in on-setting cachexia." (PMID 29394913, 2018). "Moreover, combining TIMP-1 plasma levels with cachexia status improved the prognostic value, suggesting this newly identified association between TIMP-1 and cachexia could provide a benefit for patient stratification." (PMID 29394913, 2018).
Cachexia (continued). "Furthermore, TIMP-1 appears to be counterindicated as a survival marker in patients with jaundice, while TIMP-1 and cachexia may be a promising combination of prognostic markers." (PMID 29394913, 2018). "When TIMP-1 and GDF-15 levels were dichotomized using a median split, both TIMP-1 (P<0.001) and GDF-15 (P<0.001) were significantly increased over worsening cachexia status when subjected to a Cochrane-Armitage trend test." (PMID 39989973, 2025). "When cachexia status was classified using a 4-stage system 32, we find that patients with PCa can be differentiated from NCa patients by CRP, TIMP-1 and GDF-15." (PMID 39989973, 2025). "Our results confirm this finding, demonstrating that differences in plasma TIMP-1 between PDAC, CP, and control patients are less drastic when patients with jaundice or cachexia are excluded." (PMID 29394913, 2018). "While TIMP-1 was counterindicated as a marker in combination with jaundice, combining TIMP-1 with cachexia represents a promising combination of prognostic parameters." (PMID 29394913, 2018). "Pre-cachexia stage can be differentiated by GDF-15 and TIMP-1 levels." (PMID 39989973, 2025). "In contrast, the higher TIMP-1 levels of cachexia patients did not interfere with usefulness of TIMP-1 as prognostic marker and excluding cachectic patients even reduced the association of TIMP-1 with survival." (PMID 29394913, 2018). "Further, the impact of cachexia on the usefulness of TIMP-1 as clinical progression and survival marker has not yet been evaluated." (PMID 29394913, 2018). "Thus, TIMP-1 only predicted survival in the absence of jaundice in our cohort while accounting for cachexia improved its prognostic value." (PMID 29394913, 2018). "We show for the first time that TIMP-1 may be a useful prognostic marker especially in combination with cachexia but notably, not in patients with jaundice." (PMID 29394913, 2018). "TIMP-1 levels significantly correlated with cachexia only in patients without jaundice." (PMID 29394913, 2018). "TIMP-1 could thus be overestimated as a diagnostic marker in case PDAC-related jaundice and cachexia are not accounted for." (PMID 29394913, 2018). "Interestingly, both low TIMP-1 levels and absence of cachexia were independently beneficial for survival (curve #1 vs. curve #4)." (PMID 29394913, 2018). "We also observed increased TIMP-1 plasma levels in CP and in PDAC patients with cachexia compared to those without, although these differences were not statistically significant (p = 0.149)." (PMID 29394913, 2018).
cerebral infarction (5 papers, 2019 to 2024). An ischemic condition of the brain, producing a persistent focal neurological deficit in the area of distribution of the cerebral arteries. "More interestingly, the reduced effects of exercise preconditioning on neurological deficit scores, neuronal death rate, and cerebral infarction area in MCAO rats were partially reversed by TIMP1 overexpression." (PMID 39364701, 2024). "In this study, vx-765 treatment enhanced the expression levels of TIMP-1 and TIMP-2 but reduced the expression levels of MMP-1, MMP-2, MMP-3, and MMP-9 proteins after cerebral infarction." (PMID 33584203, 2020). "We believe that those high TIMP-1 levels during the first week of cerebral infarction that we found in non-surviving compared to surviving patients do not contribute to the death of patients." (PMID 31319804, 2019). "However, there is no data about circulating TIMP-1 levels in surviving and non-surviving patients with cerebral infarction during the first week of cerebral infarction." (PMID 31319804, 2019). "The objectives of this study were to determine serum TIMP-1 levels during the first week of a severe cerebral infarction in surviving and non-surviving patients, and whether those levels during the first week could be used as a mortality biomarker for these patients." (PMID 31319804, 2019). "On the other hand, an increase in serum concentrations of TIMP-1, but not MMP-9 of the MMP-9/TIMP-1 ratio has been reported in patients with central nervous disorders, such as cerebral infarction, cranial hemorrhage, traumatic brain injury, hemolytic-uremic syndrome, and HHV-6 encephalitis." (PMID 36670630, 2022).
dilatation (5 papers, 2016 to 2024). "The current study aims to identify the role of MMP-1, MMP-2, MMP-9, and the MMP inhibitor, TIMP-1, in identifying aortic dilation in children with BAV." (PMID 39408865, 2024). "The following variables were entered into the forward selection logistic regression model as predictors associated with SPTD at <32 weeks: VDBP, TIMP-1, and DKK3 in the CVF, serum CRP, cervical dilatation, vaginal progesterone therapy, and use of corticosteroids." (PMID 28700733, 2017). "Hence, the current study proposes to identify whether three MMPs, namely MMP-1, MMP-2, and MMP-9, and the MMP inhibitor, TIMP-1, could be used to predict aortic dilatation in children with BAV." (PMID 39408865, 2024). "Of these, AF S100 A8/A9 and TIMP-1 levels were independent of other potentially confounding factors (e.g., cervical dilatation)." (PMID 34195783, 2021).
Encephalopathy (5 papers, 2016 to 2023). Encephalopathy is a term that means brain disease, damage, or malfunction. "The authors suggested that MMP-9 level and MMP9/TIMP1 ratio might indicate central nervous system damage and development of encephalopathy." (PMID 28104930, 2016). "Molecules identified for this criterion from the RNAseq dataset with a known or possible involvement in encephalopathy and delirium included miR-320a-3p, ACHE, TSPO, and TIMP1, which interacted with MMP9." (PMID 34573990, 2021). "Therefore, an increased MMP-9/TIMP-1 ratio has been suggested to impair the BBB, which ultimately leads to encephalopathy." (PMID 36670630, 2022). "In addition, the levels of MMP-9 and TIMP-1 are upregulated in premature infants with BPD and encephalopathy, which has been previously confirmed." (PMID 33263620, 2020).
experimental autoimmune encephalomyelitis (5 papers, 2011 to 2024). An autoimmune demyelinating disease of the central nervous system that is produced experimentally in animals by the injection of homogenized brain or spinal cord in Freund's adjuvant. "Additionally, TIMP-1-deficient mice experienced a significant reduction in astrogliosis during mouse experimental autoimmune encephalomyelitis (EAE)." (PMID 39329731, 2024). "To explore the functional significance of T cell derived TIMP1, we performed a passive transfer model of experimental autoimmune encephalomyelitis (EAE)." (PMID 23555662, 2013). "Evidence from other disease states including experimental autoimmune encephalomyelitis and spinal cord injury suggests that expression of TIMP-1 increases along with MMPs." (PMID 22507553, 2012).
infarction (5 papers, 2021 to 2023). A localised pathological necrosis of tissue resulting from obstruction of the blood supply usually by a thrombus, an embolus, or vascular torsion. "Though the differences were rather discreet, it is still obvious that staining of MMP-2, MMP-9, and TIMP-1 in younger wound age groups was more intense in cases with an underlying infarction compared to those with injuries of other origins." (PMID 34041592, 2021). "According to these observations, in our study, by analyzing the presence of cerebral lacunar infarcts detected by MRI, we demonstrate a positive and significant independent association between MMP-2, TIMP-1, TIMP-2, TIMP-3 and the presence of the lesions." (PMID 37959331, 2023). "The higher expression of collagens and TIMP-1 in TFΔCT hearts suggest that the balance between collagen production and degradation has moved towards more collagen and collagen fibers in the heart after infarction." (PMID 34646369, 2021).
intracerebral hemorrhage (5 papers, 2018 to 2023). A cerebrovascular disorder characterized by bleeding into one or both cerebral hemispheres including the basal ganglia and the cerebral cortex. "Some scholars have studied in traumatic brain injury (TBI) or intracerebral hemorrhage (ICH), TIMP-1, or TIMP-3 released by MSCs could stabilize BBB integrity." (PMID 29724240, 2018).
meningioma (5 papers, 2020 to 2024). A generally slow growing tumor attached to the dura mater. "As to our knowledge, none of these proteins are reported to associate with meningioma as possible serum molecular marker, however abnormal levels of TIMP-1 and OPN have been reported in meningioma tumour tissue." (PMID 34162919, 2021). "Significant fold changes were found in MMP10, TIMP1, and TIMP4 in meningioma patients." (PMID 38474106, 2024). "The authors found that TIMP-1 levels were elevated in Grade 1 and Grade 2 meningiomas, but not in Grade 3 cases and hypothesized different pathways in which TIMP-1 can be involved in the progression of meningiomas." (PMID 38137885, 2023).
metastatic colorectal cancer (5 papers, 2016 to 2023). "TIMP-1 and MMP-7 are highly sensitive and accurate diagnostic biomarkers for metastatic colorectal cancer." (PMID 34907282, 2021). "A randomized controlled study showed that in patients with metastatic colorectal cancer receiving first-line combined chemotherapy, the upregulation of plasma TIMP-1 indicates that the objective effective rate of chemotherapy is very low." (PMID 34957118, 2021).
neuropathy (5 papers, 2015 to 2023). A disorder affecting the nervous system that manifests with pain, tingling, numbness, and/or muscle weakness. "We have previously shown that mRNA for TIMP1 is upregulated in neuropathy and it is also produced by microglia/macrophages." (PMID 26090236, 2015). "A negative association of TIMP-1 was also evident with several neurophysiological tests indicating neuropathy." (PMID 33775157, 2021). "It is likely that the InF nerve injection-induced neuropathy was largely due to dramatic, but transient, increases in enzymatic activities of MMP-9 and activating TIMP-1 in the operated nerves." (PMID 35694244, 2022). "The change in the ratio between pro- (MMP-9) and antinociceptive (TIMP-1) factors, in favour of the latter may be one of the mechanisms of LPS-RSU-induced analgesia in neuropathy." (PMID 29656686, 2018). "TIMP-1 correlated with abnormal unilateral and bilateral vibratory sense foot perception (r = −0.49 and r = −0.51, respectively), foot neuropathy impairment assessment score (NIA; r = −0.55), neuropathy symptom assessment score (r = 0.42), microalbuminuria (r = 0.50) and eGFR (r = −0.45)." (PMID 33775157, 2021). "Notably, HDL2 isolated from type 2 diabetes patients with neuropathy was more potent compared to HDL2 from patients without neuropathy in upregulating MMP-1, downregulating TIMP-1, and stimulating collagenase activity in Schwann cells." (PMID 37762318, 2023).
paroxysmal AF (5 papers, 2011 to 2023). "Chromosome 4q25 variant alleles and TIMP-1 levels are also associated with clinical outcomes in those with paroxysmal AF." (PMID 36312240, 2022). "Therefore, research with a larger population is necessary to confirm the prognostic value of sST2 and TIMP-1 in identifying patients at high risk of paroxysmal AF." (PMID 36683600, 2022). "Some data suggest that plasma TIMP-1 concentrations less than 107 ng/ml combined with the absence of a variant allele at rs10033464 might predict a lower rate of paroxysmal AF recurrence after RFCA." (PMID 36312240, 2022). "The serum levels of sST2 and TIMP-1 were significantly higher in both the paroxysmal AF and persistent AF groups than those in the SR group." (PMID 36683600, 2022). "In other studies, in patients with persistent AF, TIMP-1 levels were increased when compared with patients with paroxysmal AF, and the levels of TIMP-1 were also higher in patients with paroxysmal AF than in the SR group." (PMID 36683600, 2022). "TIMP-1, sST2, BNP, and LAD were associated with the progression of AF as their levels gradually increased starting from the SR group to the paroxysmal AF group and then to the persistent AF group." (PMID 36683600, 2022). "In the present study, TIMP-1 was higher in the paroxysmal AF group than the SR group and higher in the persistent AF group than the paroxysmal AF group." (PMID 36683600, 2022). "Patients with AF had lower levels of TIMP-1 compared to those with SR while permanent AF subjects had lower TIMP-1 levels than those with paroxysmal AF (p < 0.001 for both comparisons)." (PMID 22204652, 2011). "Patients with permanent AF had lower levels of TIMP-1 than those with paroxysmal AF (p = 0.001) and the latter had lower levels of TIMP-1 than controls (p < 0.001)." (PMID 22204652, 2011). "The serum level of sST2 and TIMP-1 may be a biomarker for differentiating paroxysmal AF from SR when AF cannot be diagnosed using electrocardiography in clinical practice." (PMID 36683600, 2022). "In addition, the serum level of TIMP-1 increased significantly from the SR group to the paroxysmal AF group and then to the persistent AF group as follows: SR group 67.4 (56.9–81.3) ng/ml; paroxysmal AF group 89.7 (70.6–115.5); and persistent AF group 127.3 (87.0–173.7), p < 0.001." (PMID 36683600, 2022). "Therefore, in clinical practice, sST2 and TIMP-1 may be able to serve as biomarkers to differentiate paroxysmal AF from SR." (PMID 36683600, 2022). "However, the role of these novel biomarkers in the progression of AF is not yet clear, and neither is it clear whether serum sST2 and TIMP-1 can be detected and predict AF onset, especially the onset of paroxysmal AF." (PMID 36683600, 2022).
Peri-Implantitis (5 papers, 2020 to 2025). An inflammatory process with loss of supporting bone in the tissues surrounding functioning DENTAL IMPLANTS. "Another TIMP found in peri-implant tissues was TIMP-2, which is also downregulated in peri-implantitis, but it had a less important role in peri-implant disease than TIMP-1." (PMID 37232785, 2023). "In addition, MMP-1 may be involved in the pathogenesis of peri-implantitis, given its increase in fibroblasts from peri-implantitis and reduced gene expression of tissue inhibitors of matrix metalloproteinases (TIMP-1), which may indicate a loss of attachment around dental implants." (PMID 35163727, 2022). "As MMP-1 and MMP-8 are mainly responsible for collagen matrix destruction in peri-implantitis, the MMP-1/TIMP-1 and MMP-8/TIMP-1 ratio shifts in favor of MMPs can serve as an indicator of peri-implantitis progression and inefficiency of treatment." (PMID 37232785, 2023). "Thus, in addition to aMMP-8, MMP-8 per TIMP-1, PMN elastase and MPO, seem to be possible alternatives for BOP as more accurate indicators of peri-implant tissue destruction and peri-implantitis." (PMID 32764436, 2020).
pterygium (5 papers, 2020 to 2024). A wedge-shaped fibrovascular lesion arising from the bulbar conjunctiva and extending to the cornea. "Lastly, oxidative stress is shown to promote metalloprotease-2 (MMP-2) activity and reduce tissue inhibitor of metalloproteases-1 (TIMP-1), which are events that significantly influence the growth of the pterygium." (PMID 38611627, 2024). "In pterygium, the overexpression of MMP-1 breaks the balance between MMP-1 and TIMP-1, and the imbalance may cause pterygium to infiltrate through the normal cornea 44,45." (PMID 32218695, 2020). "In some reports of pterygium, when determining MMP-1 and its inhibitor TIMP-1, the latter was observed at levels similar to those of MMP-1, which could explain the progressive-invasive growth of the pterygium." (PMID 34361655, 2021).
thrombosis (5 papers, 2013 to 2025). "In thrombosis, TIMP1 has been shown to be significantly associated with DVT." (PMID 40432920, 2025). "We therefore believe that septic patients carrying the T allele in the 372 T/C genetic polymorphism of TIMP-1 could have a prothrombotic/antifibrinolytic profile, responsible for capillary thrombosis, multiple organ dysfunction and, finally, early death." (PMID 23706069, 2013).